LINC00571 (long independently transcribed non-coding RNA 571)
Gene: Long non-coding RNA gene on chromosome 13 (38,050,817 to 38,350,284, reverse strand). Ensembl gene ENSG00000223685.
Diseases named in the same sentence as LINC00571 in open-access papers:
LINC00571 is named in the same sentence as 6 diseases in open-access papers, as found by Europe PMC text mining. Sharing a sentence is not in itself a finding about the gene and the disease. The quoted sentences say what the papers report.
triple-negative breast carcinoma (2 papers, 2023 to 2024). An invasive breast carcinoma which is negative for expression of estrogen receptor (ER), progesterone receptor (PR), and human epidermal growth factor receptor 2 (HER2). "LINC00571 was identified as a risk factor with HR >1 for patients with triple-negative breast cancer, and high LINC00571 expression was associated with poor overall survival." (PMID 37847171, 2023). "Our study revealed that the LINC00571/HNRNPK/ILF2/IDH2 axis promoted the progression of triple-negative breast cancer by regulating tricarboxylic acid cycle metabolites." (PMID 38238853, 2024).
breast carcinoma (1 paper, 2024). "In conclusion, our study demonstrated that LINC00571 was highly expressed in breast cancer, and promoted cancer cell proliferation through the HNRNPK/ILF2-TCA cycle axis." (PMID 38238853, 2024).
myopia (1 paper, 2024). "Of these regions, 14 reached the 5e−8 threshold after meta-analysis, including a 28.1-kb region on 13q13.3 overlapping the LINC00571 gene, a lncRNA gene previously associated with myopia, schizophrenia, and, interestingly, educational attainment and tau measures." (PMID 38365752, 2024).
tumor (1 paper, 2024). "A positive correlation was revealed between the elevated expression of LINC00571 and tumor differentiation, lymphatic metastasis, distant metastasis, and Ki-67 levels in TNBC patients." (PMID 38238853, 2024). "In addition, in vivo xenograft tumor experiments revealed that the volume of xenograft tumors generated from LINC00571 knockdown TNBC cells were significantly lower than those generated from control cells, whereas LINC00571 overexpression increased the volume of xenograft tumors." (PMID 38238853, 2024).
LINC00571 also shares sentences with these, for which no sentence is quoted: cancer (1 paper); schizophrenia (1).